IL10 (interleukin 10)
Diseases named in the same sentence as IL10 in open-access papers (continued):
Sharing a sentence is not in itself a finding about the gene and the disease.
colitis (continued). "We found that sodium propionate inhibited phosphorylation of STAT3 induced by colitis, which is consistent with the previous report that multi-fiber mix feeding decreased p-STAT3 expression in colonic mucosa of IL-10-/- mice." (PMID 27574508, 2016). "Compared with the control, the serum levels of IL-1β, IL-6, IL-10, IFNγ, and TNFα were increased in DSS colitis mice." (PMID 27177331, 2016). "HUC-MSCs protected against experimental colitis by boosting the numbers of CD5+ B cells and IL-10-producing CD5+ Bregs, and correcting Treg/Th17/Th1 imbalances." (PMID 27515534, 2016). "We then generated Lcn2/IL-10 DKO mice and compared intestinal inflammation with that of IL-10 KO mice to reveal the role of Lcn2 in the development of colitis." (PMID 27734904, 2016). "Rosiglitazone induces IL-10 production in experimental colitis and Parkinson's models of disease, but in a septic lung 15d-PGJ2 and pioglitazone reduced IL-10 expression." (PMID 26713087, 2015). "IL-10−/− PCs remained able to produce TGF-β and ameliorate DSS-induced colitis, but were less efficacious than PCs from wild-type mice, as indicated by the disease activity score and colon length." (PMID 26565726, 2015). "The CTX treatment in TNBS-mice also induced a secretion of TGF-β, IL-10, PGE2 and LXA4 accompanied by CD4+FoxP3+ cells, suggesting their participation in the improvement of the colitis induced by TNBS." (PMID 25853847, 2015). "A mono-association study, in which a single strain of bacteria was inoculated into germ-free IL-10-deficient mice, demonstrated that E. coli induced cecal inflammation, Enterococcus faecalis induced distal colitis, and Pseudomonas fluorescens did not cause colitis." (PMID 25420450, 2015). "In contrast to the generally beneficial effects of vitamin, in a hybrid IL10−/−/CD4+transfer/piroxicam model of colitis, vitamin D supplementation exacerbated bone mineral density degradation induced by colitis." (PMID 27417758, 2015). "For example, IL-10 knockout mice with a C3H and BALB/c background are known to develop spontaneous colitis more frequently than wild-type C57BL/6 mice." (PMID 26561503, 2015). "Third, we isolated LPMCs from colonic tissues of IL-10 KO and OPN/IL-10 DKO mice, and examined their phenotype during colitis." (PMID 26274807, 2015). "In patients with IBD, the production of the inflammatory cytokines TNF-α, IFN-γ, IL-6, IL-1β, IL-10 and IL-12 are in agreement with the results of the TNBS model of colitis." (PMID 26561804, 2015). "Treatment of mice with a single dose of curli heightens transcript levels of Il10 in the colon and ameliorates the disease pathology in TNBS-induced colitis." (PMID 26855788, 2015). "The macrophage phenotype during colitis was compared between IL-10 KO and OPN/IL-10 DKO mice to determine the effect of OPN on macrophage function in vivo." (PMID 26274807, 2015). "Glycyrrhizin has been reported to decrease IFN-γ, IL-12, and IL-17 and increase IL-10, ameliorating TNBS-induced colitis in mice." (PMID 25866535, 2015). "To analyze the effect of the hydatid LL on cytokine production in vivo during DSS-induced colitis, we measured the levels of proinflammatory cytokines (TNF-α, IFN-γ) and the immunoregulatory cytokine IL-10 by ELISA in plasma from mice." (PMID 25844068, 2015). "Moreover, macrophages isolated from IL-10 deficient mice display enhanced NOD2-dependent pro-inflammatory activity in which the well-known synergistic activity of MDP and TLR ligands is intrinsically hyper-responsive to bacterial stimulus, contributing to the development of colitis." (PMID 25071778, 2014). "Although R243 treatment reduced IL-10 secretion, its overall suppression of TNF-α and IL-6, together with inhibition of inflammatory cell infiltration, seemed to ameliorate colitis." (PMID 24714157, 2014).
colitis (continued). "Very recently, our group reported that a single strain of Clostridium butyricum induced intestinal IL-10-producing macrophages via TLR2 and suppressed a mouse model of acute experimental colitis." (PMID 24904576, 2014). "Previously, upregulation of IL-10 has been reported in plasma of patients with IBD and colons of rats with TNBS- and dextran sulfate-induced colitis." (PMID 24831514, 2014). "Administration of TLM lowered TNF-α, PGE2 and IL-10 by 49%, 39% and 51% respectively, as compared to TNBS colitis group." (PMID 24831514, 2014). "Intestinal inflammation in the adoptive transfer colitis model examined by ELISA was also characterized by higher concentrations of IFN-γ, IL-17A and IL-10 in the colon supernatants compared with CONTROL mice." (PMID 25313594, 2014). "We have investigated the production of cytokines including IFN-γ, IL-1β, IL-6, IL-10, IL-12 (P40), IL-12 (P70), IL-17, and TNF-α in colonic mucosa of mice with experimental colitis." (PMID 24948848, 2014). "pcDNA3.0 carrying murine IL-4 or IL-10 cDNA was encapsulated with LipofectAMINE 2000 and intraperitoneally injected into mice with TNBS-induced colitis." (PMID 24314293, 2013). "This study further investigated the effect of IL-4 (IL-4), IL-10 and their combination on treatment of trinitrobenzenesulfonic acid (TNBS)-induced murine colitis." (PMID 24314293, 2013). "FOXP3+ cells, CD4+CD25+FOXP3+ cells, and IL-10-secreting CD4+CD25+ T cells all play key roles in the regulation and suppression of DSS-induced colitis." (PMID 23864893, 2013). "At 15 DPI in mice with colitis, the production of IL-12p70 and MCP-1 increased and production of regulatory cytokines TGF-β, IL-10 and IL-6 decreased." (PMID 24167594, 2013). "In models of colitis driven by IL-17A+ or IL-17A+IFN-γ+ T cells, suppression of disease by Foxp3+ Treg or Tr1 cells required direct IL-10 signaling into the effector T cells." (PMID 23405904, 2013). "This was reflected by a downregulated Th1 (TNF-α, IFN-γ, IL-6, IL-1β, and IL-12) cytokine response of immune cells and stimulated IL-10 and TGF-β production in TNBS-induced colitis." (PMID 23691339, 2013). "These probiotic bacteria can promote production of IL-10 and Tregs and ameliorate TNBS-induced colitis." (PMID 23772228, 2013). "AhR−/− mice are more sensitive to DSS colitis than WT mice while AhR−/+ mice are less sensitive and exhibit a decreased expression of TNF and IL-17 and an increased expression of IL-10 as we observed in our model." (PMID 23638007, 2013). "To further confirm the therapeutic effect of IL-4 and IL-10 gene therapy, we performed qRT-PCR analysis of their expression in TNBS-induced murine colitis tissues." (PMID 24314293, 2013). "Colitis was induced in BALB/c mice by oral administration of dextran sodium sulphate; mice were then treated with interleukin-10 plus anti-IL-1 antibody at low dosage." (PMID 27785242, 2013). "The level of IL-10 and TGF-β that have been shown to have a regulatory effect in experimental colitis were also analyzed." (PMID 23198878, 2012). "Colons and mesenteric lymph nodes were harvested 7 days after the induction of colitis, and the expression of IFN-γ, IL-6, IL-17, IL-4, and IL-10 mRNA was quantified by real-time PCR." (PMID 22479648, 2012). "We used specific pathogen free (SPF) streptomycin-pretreated mouse colitis model that included healthy C57BL/6 and immunocompromised iNos−/−, IL10−/− and CD40L−/− in the background of C57BL/6 mice to assess the efficacy of developed vaccine candidate." (PMID 23284865, 2012). "All doses of anthocyanins extract from blueberries significantly reversed the increase in IL-12, TNF-α and IFN-γ levels, which were all high in TNBS control, and the production of IL-10 was up-regulated, which was inhibited in TNBS-induced colitis in mice." (PMID 21785630, 2011).
colitis (continued). "L. casei DN-114 001 prevented the development of acute DSS-induced colitis in TLR4 KO mice by inhibiting myeloperoxidase activity and IL-12p40, and increasing TGF-β and IL-10 mRNA." (PMID 21991534, 2011). "CXCL10 and its receptor CXCR3 have been shown to be upregulated in IL-10 knockout (IL-10−/−) mice and those with dextran sulphate sodium (DSS)-induced colitis." (PMID 20360984, 2010). "IL-4, IL-10 and INF-y concentrations (ρg/mL), MPO activity (U/mg) in the colon and DNA damage levels (tail moment/100 cells isolated from colon) of DSS-induced colitis rats fed Control, Fish or Soybean/Fish diet." (PMID 20615224, 2010). "Acute C. rodentium-induced colitis in C57BL/6J mice and chronic spontaneous Helicobacter-dependent colitis in TLR4−/− x IL-10−/− mice were utilized for evaluation." (PMID 20976045, 2010). "We examined levels of IL-6, IL-10, IL-17A, and IL-23 in the colons following 7 days of cis-UCA treatment, and also following the induction of colitis." (PMID 21060867, 2010). "In chronic DSS-induced colitis, both decreased expression of pro-inflammatory cytokines (TNF-α, NO, and IL-1β) and increased anti-inflammatory mediators (IL-10) in the colonic mucosa contributed to attenuate inflammation after Resveratrol treatment." (PMID 21151942, 2010). "Thus, in the presence of IL-23R-responsive WT T cells there is a reduction in the ability of Il23r−/− T cells to produce IL-10, which may explain the development of colitis in mice given a mixture of WT and Il23r−/− T cells, despite increases in the percentage of Foxp3+ Treg cells." (PMID 20732640, 2010). "Blockade of the CXCL10-CXCR3 axis with monoclonal anti-CXCL10 antibodies ameliorates colitis in IL-10−/− mice by decreasing infiltrating T cells, and confers protection from DSS-induced colitis." (PMID 20360984, 2010). "We demonstrate here that the AOM/Il10−/− model of CAC can be used to investigate specifically, the impact of colitis on colorectal tumorigenesis." (PMID 19551144, 2009). "A neutralizing antibody against IL-6 receptor prevents colitis in TNBS colitis and in IL-10−/− mice as well as in T-cell transfer colitis." (PMID 18545662, 2008). "DSS colitis in the VDR KO mice was accompanied by high colonic expression of TNF-α, IL-1 α, IL-1β, IL-12, IFN-γ, IL-10, MIP-1α and KC." (PMID 17397543, 2007). "Samples were collected 7 days after colitis induction, for intestinal bacterial flora, bacterial translocation, short chain fatty acids (SCFAs), myeloperoxidase (MPO), cytokines (IL-1β, TNF-α, IL-10 and TGF-β) and malondialdehyde (MDA)." (PMID 17069659, 2006). "We found that intra-peritoneal administration of adenoviral IL-10 to mice significantly reversed colitis induced by administration of 3% DSS (dextran sulfate), a common model of colitis." (PMID 16259632, 2005). "Consistently, MyD88 signaling in myeloid cells is required to initiate inflammatory T cell responses and colitis induced by pathobionts such as Hh in the absence of IL‐10 signaling." (PMID 41328802, 2026). "Consistent with previous reports that IL-10–producing Breg cells exert potent anti-inflammatory effects in the intestine, our findings demonstrate that B. adolescentis Bifi-94 and its PG enhance IL-10 production and ameliorate DSS-induced colitis." (PMID 41511071, 2026). "Several in vivo studies further support its protective role: dietary ARA reduced ER stress, oxidative damage, and fibrosis in Il10−/− mice, and did not exacerbate colitis in DSS models, except at very high doses." (PMID 41261441, 2025). "We found that, unlike Il10−/− mice, Gsta4−/− and Il10−/−/Gsta4−/− mice colonized with E. faecalis failed to develop colitis or CRC." (PMID 39819335, 2025). "In mice with DSS-induced colitis, levels of the pro-inflammatory cytokines TNF-α, IL-1β, and IL-6 were significantly elevated, whilst the anti-inflammatory cytokine IL-10 was markedly decreased, indicating an intense inflammatory response and immune dysregulation." (PMID 40777179, 2025).
colitis (continued). "Below, we summarize key findings from both chemically induced colitis models (e.g., DSS, TNBS) and genetically engineered spontaneous models (IL-10 KO, Winnie, SAMP1/YitFc), each providing mechanistic insights into eosinophil functions and interactions in IBD pathogenesis." (PMID 40860650, 2025). "To test this hypothesis, we colonized Gsta4−/− and Il10−/−/Gsta4−/− mice with E. faecalis OG1RFSS, or PBS as control, for 9 months and evaluated for colitis and CRC." (PMID 39819335, 2025). "Also, breeding SvEv129 IL-10–/– in a germ-free facility protects against colitis because MMTV uses the microflora for entry into small intestine in weanling pups, while also triggering the production of IL-10 to tolerize the host to infection." (PMID 39817448, 2025). "Administration of egg yolk-derived SPM accelerates inflammatory injury in the colon of mice treated with dextran sulphate sodium (DSS) and IL-10 negative mice used as a spontaneous colitis model." (PMID 40137112, 2025). "In models of acute or systemic inflammation, including carrageenan-induced pleurisy, nociception and paw edema, and DSS-induced colitis, treatment decreased leukocyte migration, Th1/Th17 polarization, levels of pro-inflammatory cytokines (IL-6, TNF-α, IFN-γ) and increased IL-10." (PMID 41470797, 2025). "Our functional data show that DSS-colitis increases the number of active nodose ganglia neurons at baseline, possibly owing to altered membrane excitability, with a reduction in the amplitude of cytokine-specific responses (TNF and IL-10)." (PMID 40268933, 2025). "To decipher whether Foxp3creCREBfl/fl T cells prevent colitis through IL-10 production and/or ST2 expression, we performed an adoptive transfer colitis experiment with anti-IL10R antibodies or recombinant soluble ST2 (sST2)." (PMID 40777015, 2025). "To investigate the physiological role of LGG-induced IL-10 and its effector cells in gut, we profiled the distribution of the IL-10 receptor (IL-10R) among different immune cells isolated from the MLNs in DSS-induced colitis mice with LGG treatment." (PMID 39895628, 2025). "IL-10−/− animals have an intact epithelial barrier but progressively develop spontaneous colitis due to hyperinflammatory responses of macrophages to the microbiota, which are not counteracted by Treg-derived IL-10." (PMID 40471139, 2025). "In DSS-induced colitis, UA lowered IL-6 levels and attenuated inflammatory cell infiltration, while in LPS-induced lung injury, it suppressed TNF-α, IL-1β, and IL-6 production while upregulating anti-inflammatory IL-10 expression." (PMID 40804950, 2025). "Previously, cercariae of S. japonicum infection has been shown to provide immediate protection against dextran sodium sulphate (DSS)-induced colitis in mice model, by which cercariae suppressed splenic interferon (IFN)-γ and increased splenic IL-10 and regulatory T (Treg) cells." (PMID 40332187, 2025). "After DSS-induced colitis, no major differences in terms of IL-10 secretion were observed comparing Mgat5−/− and Mgat5WT mice." (PMID 39918275, 2025). "This parameter allowed us to increase the number of datapoints for the statistical analysis, as several IL-10-/- mice developed mild or transient colitis symptoms without having to be sacrificed." (PMID 39843997, 2025). "has shown that oral gavage of A. muciniphila for over 7 weeks could induce colitis in germ-free and SPF IL-10-/- mice." (PMID 41488633, 2025). "As expected, there were no obvious differences in weight change, colon length, colitis scores and the ratio of mesenteric weight to body weight between Il‐10−/– mice receiving miR‐132‐3p antagonized CrF‐EVs and untreated Il‐10−/– mice." (PMID 39623906, 2024). "In specific pathogen-free environments, mice lacking the interleukin (IL)-10 gene (IL-10-/-) develop colitis, while in sterile environments, they do not." (PMID 38398870, 2024).
colitis (continued). "Mice lacking Il10 in Treg exhibit mild colitis, but no autoimmunity, while mice with deletion of Prdm1 in Treg show signs of autoimmunity only in aged mice." (PMID 38655862, 2024). "The qRT‐PCR results demonstrated significantly elevated levels of pro‐inflammatory factors (IL‐6 and TNFα) in colons of the colitis animal model, while no significant change in the levels of anti‐inflammatory cytokines (IL‐10) was observed." (PMID 38340032, 2024). "OMVs secreted by Bacteroides fragilis carries polysaccharide A (PSA), which is delivered to intestinal dendritic cells and induces CD4 regulatory T cells (Tregs) to produce IL-10, which down-regulates the inflammatory response and effectively ameliorates DSS-induced colitis." (PMID 39628464, 2024). "In line with our results in Il10−/−Mdr2−/− mice, colitis severity and CD4+ T-cell infiltration in the inflamed colon of Il10−/− mice was attenuated under the DDC diet, and frequencies of colonic Foxp3+ Treg cells were increased compared with the regular chow diet." (PMID 38839272, 2024). "In DSS-induced colitis, pre-treatment with DHA-PL and DHA-enriched triglyceride (DHA-TG) for 14 days downregulated pro-inflammatory IL-1β and TNF-α and upregulated anti-inflammatory IL-10 protein expressions." (PMID 38672464, 2024). "Here, in the zebrafish colitis model, DSF treatment significantly inhibited the abnormal increase in the expression of pro-inflammatory cytokines (tnfa, il1b, and il6) and the decrease in the expression of the anti-inflammatory factor il10." (PMID 38892496, 2024). "Results showed that the IL-10 production in MLN was upregulated when the mice were induced colitis by DSS in the presence or absence of T. spiralis infection, antibiotic treatment, or cohousing (P <0.05)." (PMID 39495798, 2024). "A large cohort study suggests that a lack of IL10 or IL10 receptors can lead to severe colitis in newborns, which can be life-threatening and accompanied by multiple extraintestinal manifestations." (PMID 39687875, 2024). "The increase in local IL-10 concentration at the peak of the disease was not pronounced in either group of C57BL/6 mice subjected to the induction of experimental colitis." (PMID 38892639, 2024). "Mouse-adaptation in the inflamed Il-10−/− host reassembled a more aggressive microbiota that induced more severe colitis in serial transplant to Il-10−/− mice than the distinct microbiota reassembled in non-inflamed WT hosts." (PMID 39113097, 2024). "Despite not witnessing significant alterations in TNF-α and IL-10 levels in the current DSS-induced colitis model, we expect such modifications to occur with concentration and duration adjustments." (PMID 38539873, 2024). "Additionally, a recombinant anti-inflammatory protein, AIP-1, derived from the ESP of Ancylostoma caninum, has been shown to modulate anti-inflammatory cytokines such as IL-10 and TGF-β in a mouse colitis model." (PMID 39596069, 2024). "Additionally, at doses of 20 and 40 mg/kg, ferulic acid ameliorated TNBS-induced colitis by inhibiting the production of proinflammatory cytokines (TNF-α, IL-1β, IL-6, AND IL-10) and downregulating COX-2 synthesis." (PMID 38732594, 2024). "Similarly, in a mouse model of colitis induced by CD3 monoclonal antibody + tamoxifen, the induction of IL-10-producing Th17 was found to inhibit inflammatory reactions." (PMID 38317142, 2024). "This exposure may contribute to colitis by altering the intestinal barrier, decreasing LCA and DCA, altering the TH17/Treg balance, increasing IL-17A, and downregulating IL-10." (PMID 39767816, 2024). "For instance, germ-free mice lacking interleukin-10 (IL-10 KO) developed mild inflammation in the cecum, while Enterococcus faecalis colonization led to distal colitis." (PMID 38690290, 2024). "NLRP6 deficient animals are enriched for A. muciniphila and display higher intestinal inflammation, and IL10-/- NLRP6 -/- mice develop spontaneous colitis in a facility where IL10-/- mice do not." (PMID 39305271, 2024).